CTLA4 (cytotoxic T-lymphocyte associated protein 4)
Diseases named in the same sentence as CTLA4 in open-access papers (continued):
Sharing a sentence is not in itself a finding about the gene and the disease.
non-small cell lung carcinoma (continued). "Formenti and colleagues have recently reported clinical outcomes and translational readouts from a trial that seeks to address this question using anti-CTLA-4 immunotherapy and palliative radiation in patients with non-small cell lung cancer (NSCLC)." (PMID 30841910, 2019). "In general, immune checkpoint blockade through monoclonal antibodies targeting PD-1, PD-L1, and/or CTLA-4 have shown unprecedented activity in several metastatic malignancies, including melanoma and Non-Small Cell Lung Cancer (NSCLC)." (PMID 29020964, 2017). "In fact, antibody-mediated blockade of CTLA-4 and PD-1, alone or in combination, have led to unprecedented responses in refractory, metastatic melanoma, as well as in renal cell carcinoma and non-small cell lung cancer." (PMID 25941561, 2015). ", and CTLA-4 gene expression in real-time PCR assay in non-small-cell lung cancer (NSCLC) tissue samples." (PMID 23936819, 2013). "This meta-analysis has included the highest number of trials studying the efficacy and safety of first-line PD-1/PD-L1 inhibitor in combination with CTLA-4 inhibitor in the treatment of patients with advanced non-small cell lung cancer, to the best of our knowledge." (PMID 39981238, 2025). "Besides, the combination of PD-1/PD-L1 and CTLA-4 for advanced non-small cell lung cancer is currently a prominent research focus, although its clinical applicability has not achieved consensus." (PMID 39981238, 2025). "Cadonilimab, a novel PD-1/CTLA-4 bispecific antibody, has demonstrated promising antitumor efficacy across multiple solid tumors, including cervical cancer, gastric cancer, hepatocellular carcinoma, and non-small cell lung cancer." (PMID 40861473, 2025). "Additionally, studies have shown that the up-regulation of CTLA-4 expression on NK cells negatively regulates the maturation of DCs in human non-small cell lung cancer (NSCLC)." (PMID 39221244, 2024). "Interestingly, we observed a relatively higher correlation between the CD4_Pro_MKI67 and CD4_Treg_CTLA4 subsets, which is consistent with their known immunosuppressive roles in non-small cell lung cancer." (PMID 38596689, 2024). "Inhibitors targeting programmed death-1 (PD-1), programmed death-ligand 1 (PD-L1) and cytotoxic T lymphocyte-associated antigen-4 (CTLA-4) have been successfully approved for the clinical treatment of various malignant tumors such as malignant lymphoma and non-small cell lung cancer." (PMID 39687879, 2024). "Additionally, ipilimumab, an anti-CTLA-4 antibody, is presently being studied as a possible therapeutic option for a range of cancer types, including prostate cancer, non-small-cell lung carcinoma (NSCLC), renal cell carcinoma (RCC), and other malignancies." (PMID 38077327, 2023). "Several agents including Ipilimumab (anti-CTLA-4) and Nivolumab (anti-PD-1) are effective in the management of patients with melanoma, small cell and non-small cell lung cancer (NSCLC), and renal cell carcinoma (RCC), and are FDA-approved first-line treatments for patients with advanced disease." (PMID 36911698, 2023). "We analyzed the variation of circulating immune suppressive-like cell subsets and exhausted immune cells in three non-small cell lung cancer patients treated with the combination of anti-CTLA-4 plus anti-PD-1 plus anti-LAG-3 at T0 (baseline), T1 (after 2 months) and T2 (after 4 months)." (PMID 34122429, 2021). "Immune checkpoint blockers, including anti-cytotoxic T lymphocyte-associated protein (CTLA)-4 and anti-PD1/PD-L1, have been approved by the U.S. Food and Drug Administration (FDA) and are used for the treatment of melanoma and non-small-cell lung carcinoma (NSCLC)." (PMID 32276342, 2020). "Recent clinical trials have shown increased benefit of anti-PD1 and anti-CTLA4 antibodies for the treatment of non-small-cell lung cancer (NSCLC) tumors with high TMB, defined as tumors with >10 mutations per megabase or as tumors with great than a median of 158 mutations." (PMID 31440245, 2019).
non-small cell lung carcinoma (continued). "In line with this, studies analyzing the response rates of patients with cancer to ICB, such as anti-CTLA-4 in melanoma or anti-PD-1 in non-small cell lung cancer (NSCLC), observed a positive correlation between the mutational burden and the efficacy of the therapy." (PMID 31535086, 2019). "examine non-small-cell lung cancers treated with combined PD-1 and CTLA-4 blockade using whole-exome sequencing and find that high tumor mutation burden is the strongest feature associated with improved objective response, durable benefit, and progression-free survival in multivariable analysis." (PMID 29657128, 2018). "Better survivability for the early-stage OSCC patients suggests that CTLA4 might be overexpressed on the surface of early-stage tumor cells, as have been observed on cancer cell lines as well as in non-small cell lung carcinoma." (PMID 28174608, 2017). "higher expression of CTLA4 predicts worse survival in Non-Small-Cell Lung Cancer." (PMID 26384298, 2015). "Likewise, it has been found that the newer targeted therapy, including inhibitors of EGFR, ALK, PI3K/AKT/mTOR, RAS-MAPK, RET, MET, BRAF, and NTRK/ROS1, as well as PD1 and CTLA4 molecules, for non-small cell lung cancer (NSCLC) have far better treatment responses than the standard therapies." (PMID 39157206, 2024). "Immune checkpoint inhibitors (ICIs) are highly concerned in the treatment of non-small cell lung cancer (NSCLC), represented by inhibitors of programmed death protein 1 (PD-1) and its ligand (PD-L1), and inhibitors of cytotoxic T lymphocyte-associated antigen-4 (CTLA-4)." (PMID 36761426, 2022). "For example, antibodies against cytotoxic T-lymphocyte antigen 4 (CTLA4), programmed cell death protein 1 (PD-1) and its ligand (PD-L1) target immune checkpoints and activate immune cells to better fight cancers, such as melanoma and non-small-cell lung cancer (NSCLC)." (PMID 34976002, 2021). "Several immune checkpoints have been used to treat numerous cancer types, such as melanoma, bladder, non-small cell lung cancer (NSCLC), and CRC, with the most popular being cytotoxic T-lymphocyte antigen-4 (CTLA-4) and programmed cell death ligand-1 (PD-L1)." (PMID 40356923, 2025). "In non-small cell lung cancer (NSCLC), tumour cells expressed programmed death-ligand 1 (PD-L1) after treatment with anti-CTLA-4 antibody." (PMID 40725864, 2025). "Treatment with anti-PD-1, anti-CTLA-4, or interferon alpha-2b was given to patients diagnosed with metastatic or unresectable melanoma, renal cell carcinoma (RCC), non-small cell lung cancer (NSCLC), or neuroendocrine tumors (NET)." (PMID 40406094, 2025). "ICIs like PD-1/PD-L1 and CTLA-4 inhibitors have been particularly effective in improving survival outcomes in several cancers, including HCC, melanoma, and non-small cell lung cancer (NSCLC)." (PMID 41211067, 2025). "Immune-related genes, such as PD-1, PD-L1, and CTLA4, have been successfully used in tumor immunotherapy and have been shown to have a significant effect on B cell lymphomas, HCC, and non-small cell lung cancer." (PMID 38514488, 2024). "Immune-checkpoint inhibitors (ICIs) targeting such molecules (e.g. PD-1, PD-L1, or CTLA4) have been established as effective cancer treatments, particularly for endometrial cancer, melanoma, renal cell carcinoma (RCC) and non-small-cell lung cancer (NSCLC)." (PMID 38194216, 2024). "The EMT phenotype is positively correlated with PD-L1, PD-L2, PD-1, TIM-3, B7-H3, BTLA, and CTLA-4 expression, as well as CD4+ Foxp3+ Tregs expansion in non-small cell lung cancer (NSCLC)." (PMID 37152039, 2023). "ICIs immunotherapy consisting of anti-CTLA4 and anti-PD1 has been shown to be effective in non-small cell lung cancers and oropharyngeal cancer, and the feasibility of applying immunotherapy to cervical cancer is receiving increasing attention and research." (PMID 37400520, 2023).
non-small cell lung carcinoma (continued). "Others also reported the occurrence of abscopal responses in non-small-cell lung cancer (NSCLC) patients treated with radiotherapy and anti-CTLA-4, accompanied by the production of IFN-β cytokine." (PMID 35008385, 2022). "For example, some target genes of the common IC-lncRNA RP11-445H22 have been used as anticancer drugs targets, such as CTLA4 as a target of radotinib in cutaneous melanoma, EGFR and ERBB2 as targets of afatinib in metastatic non-small-cell-lung-cancer." (PMID 36463330, 2022). "For example, the response rate of anti-PD1/PD-L1 monotherapy or combination therapy is only about 30% in non-small cell lung cancer (NSCLC), but the irAEs’ incidence of anti-CTLA-4 inhibitors is nearly 70% in 1265 oncologic patients from 22 clinical trials." (PMID 35831836, 2022). "For example, the latest study suggested that a combination of anti-CTLA4 and anti-PD1 against metastatic melanoma and non-small-cell lung carcinoma (NSCLC) increased the patient’s life expectancy and inhibited metastasis." (PMID 36297426, 2022). "At present, the immune checkpoint inhibitors approved by the FDA for the treatment of non-small cell lung cancer are PD1/PD-L1 inhibitors and CTLA-4 inhibitors." (PMID 34391428, 2021). "Our results showed that among all non-small cell lung cancer (NSCLC) patients, when the data from anti-PD-1/PD-L1, anti-CTLA-4, and anti-MUC1 drugs are combined, the mean hazard ratios (HR) of smokers and non-smokers were 0.751 and 1.016, respectively." (PMID 34575691, 2021). "Single-cell sequencing data showed that CREM is highly expressed in the CD4+ CTLA4 and CD8+ LAYN population in non-small cell lung cancer, and CREM is highly expressed in the CD8+ T-cell exhaustion population in glioma." (PMID 34938728, 2021). "Yet, in non-small cell lung cancer (NSCLC) and when expressed in the hepatic hilar region of extrahepatic bile duct cancer patients, studies determined that CTLA-4 correlated with improved survival." (PMID 33384695, 2020). "Recent studies have shown that tumor cell-intrinsic checkpoint molecules such as IDO, PD-1, CTLA-4 and VISTA likely play important roles in the development of non-small cell lung cancer." (PMID 31159203, 2019). "Active clinical trials involving the use of both radiotherapy and immunotherapy such as cancer vaccines, CTLA-4 inhibitors, PD-1 inhibitors, and PD-L1 inhibitors in Stage III non-small cell lung cancer (NSCLC)." (PMID 28929083, 2017). "Additionally, ICIs have been particularly impactful in the treatment of advanced non-small cell lung cancer (NSCLC), where therapies targeting CTLA-4, PD-1, and PD-L1 have shown promise." (PMID 40959381, 2025). "Certain miRNAs directly influence checkpoint molecules like PD-1, PD-L1, and CTLA-4; for instance, miR-200 downregulates PD-L1 and predicts ICI response in non-small-cell lung cancer, while oncogenic miRNAs such as miR-21 promote PD-L1 increase and inhibit PTEN, aiding immune evasion." (PMID 41463227, 2025). "In addition, anti-PD-1/PD-L1 inhibitors are now standard therapies in the first-line setting for metastatic non-small cell lung cancers (NSCLC), in combination with cytotoxic therapies or CTLA-4 inhibitors, as well as in small cell lung cancer (SCLC)." (PMID 35247086, 2022). "In non-small cell lung cancer (NSCLC), the combination of anti-CTLA4 and anti-PD1 has been shown to delay time to deterioration compared to chemotherapy and resulted in an overall response rate of 30% in the CheckMate 568 study of 288 patients with stage IIIB/IV NSCLC." (PMID 34976006, 2021). "In fact, in recent years, new and effective therapeutic options involving the use of drug agents targeting CTLA-4, PD-1, and PD-L1 were developed against several solid tumors, including melanoma, renal cell carcinoma (RCC), and non-small cell lung cancer (NSCLC)." (PMID 33925671, 2021).
non-small cell lung carcinoma (continued). "Some miRNAs can act as tumor suppressors by targeting immune checkpoint molecules, such as PD-L1, PD-1, CTLA-4, and TIM-3, in tumor cells, such as ovarian cancer, prostate cancer (PC), and non-small cell lung carcinoma (NSCLC) or immune cells, such as T cells and DCs in the TIME." (PMID 33868269, 2021). "Besides melanoma patients, especially patients suffering from non-small cell lung cancer (NSCLC) benefit from treatment with antibodies inhibiting the PD1 and CTLA4 immune checkpoints." (PMID 34853305, 2021). "In non-small cell lung carcinomas (NSCLS), there was a favorable effect of CTLA-4 overexpression on overall survival, a finding which might appear in contrast with the commonly accepted notion that CTLA-4 is an important inhibitory molecule of the T-cells." (PMID 29672601, 2018). "In recent times, a major advance in the treatment of non-small cell lung cancer (NSCLC) has been the use of immunotherapy, such as immune checkpoint inhibitors targeting cytotoxic T lymphocyte antigen-4 (CTLA-4), programmed death receptor-1 (PD-1) and programmed death receptor ligand-1 (PD-L1)." (PMID 29872507, 2018). "Recently, CTLA4 overexpression was also detected in non-squamous type of non-small cell lung cancer and correlated with low Ki-67 expression and reduced death rate." (PMID 23936412, 2013). "Moreover, the combined use of autophagy inhibitors and PD-1 or CTLA-4 immune checkpoint blocking monoclonal Abs (mAb) increases Cytotoxic T lymphocytes (CTL) infiltration in murine models of PDAC and non-small cell lung cancer (NSCLC), indicating a promising therapeutic approach for these tumors." (PMID 40611330, 2025).
colitis (329 papers, 2011 to 2026). Inflammation of the colon. "In contrast, the use of Cytotoxic T-lymphocyte-associated antigen 4 (CTLA-4) inhibitors, such as ipilimumab, resulted in a notable increase in the incidence of colitis to 7%." (PMID 40165945, 2025). "By blocking inhibitory pathways like PD-1 and CTLA-4, these therapies can lead to the loss of immune tolerance, causing the immune system to attack healthy tissues and resulting in conditions such as colitis, pneumonitis, and hepatitis." (PMID 40075668, 2025). "Colitis has emerged as a leading cause of mortality in individuals treated with anti-CTLA-4 antibodies." (PMID 39759851, 2025). "CTLA-4 inhibitors are more commonly linked to colitis, hypophysitis, and rash, whereas PD-1/PD-L1 inhibitors are more often associated with thyroid dysfunction and pneumonitis." (PMID 41159031, 2025). "In mouse studies, a probiotic blend containing four Bifidobacterium species was found to lower systemic inflammatory cytokine levels and alleviate colitis caused by anti-CTLA4 treatment and dextran sodium sulfate (DSS).." (PMID 40264971, 2025). "Unfortunately, immune-related adverse events have been associated with anti-CTLA4 antibodies including the following: vitiligo, colitis, hepatitis, endocrinopathies, inflammatory polyneuropathies, myasthenia gravis, and immune-mediated cytopenia." (PMID 39934899, 2025). "Mechanistically, anti–PD-1/PD-L1 agents more commonly induce thyroiditis and pneumonitis, whereas anti–CTLA-4 therapies are particularly associated with hypophysitis and colitis." (PMID 41341585, 2025). "Gastrointestinal disorders represent the most common type of Grade 3 or higher imAEs, with colitis particularly frequent in association with CTLA‐4 inhibitors." (PMID 40538456, 2025). "The causes of death varied by treatment type: colitis was frequently associated with anti-CTLA-4 related fatalities, while pneumonitis, hepatitis, and neurotoxic effects were more common in anti-PD-1/PD-L1 related deaths." (PMID 39881252, 2025). "It is also a leading cause of fatal ICI-related adverse events: among 193 anti-CTLA-4-related deaths, colitis accounted for 70.0% (135 cases)." (PMID 41221037, 2025). "We tested the therapeutic potential of LGG to suppress ICB-associated colitis in mice treated with a combination of anti–CTLA-4 and anti–PD-1 antibodies in addition to DSS." (PMID 39895628, 2025). "Colitis is the most common lower GI irAE and a hallmark toxicity of anti-CTLA-4 therapy, with clear class-specific patterns and clinical implications." (PMID 41221037, 2025). "Immunotherapy-related colitis (irC) can pose life-threatening risks and is among the most common irAE associated with anti-CTLA-4 and dual anti-PD-1/anti-CTLA-4." (PMID 39666007, 2025). "Previous evidence has suggested that the treatment class most associated with hypophysitis and colitis is anti-CTLA-4." (PMID 38372756, 2024). "Blockade of CTLA-4 and PD-1 are linked to checkpoint inhibitor induced colitis in cancer patients, and genetic variants in Ctla4 are linked to predisposition to IBD62,63." (PMID 39496592, 2024). "Conversely, high-grade immune-related adverse events (irAEs), such as hepatitis, pneumonitis, thyroiditis, dermatitis, and colitis were linked to both CTLA-4 inhibition and PD-1/PD-L1 blocking." (PMID 38165484, 2024). "Among the various gastrointestinal irAEs associated with immune checkpoint inhibitors, colitis is the most common occurrence during CTLA-4 inhibitor therapy." (PMID 38410506, 2024). "Combination regimens of PD-1/PD-L1 and CTLA-4 inhibitors were associated with higher rates of fatigue, nausea, rash, and diarrhea/colitis." (PMID 38410506, 2024). "Studies suggest that colitis induced by CTLA-4 inhibitors tends to appear later than colitis caused by PD-1/PD-L1 inhibitors." (PMID 39451777, 2024).